INS (insulin)
Diseases named in the same sentence as INS in open-access papers (continued):
Sharing a sentence is not in itself a finding about the gene and the disease.
Obesity (continued). "Obesity, particularly during adolescence, has emerged as a significant risk factor for MS, acting through immunometabolic mechanisms such as chronic low-grade inflammation, insulin resistance, and dysregulated adipokine signaling." (PMID 41750224, 2026). "Additionally, vitamin B12 plays a critical role in lipid metabolism, and its deficiency can disrupt lipid synthesis, insulin resistance, and mitochondrial function—all of which are associated with obesity-related metabolic disturbances." (PMID 40667440, 2025). "Obesity is a known risk factor for dementia, and the weight loss induced by metformin, or its underlying mechanisms—such as its ability to reduce insulin levels—suggests it may help lower the risk of dementia." (PMID 40017057, 2025). "In patients, fasting serum insulin levels were significantly associated with obesity." (PMID 41488138, 2025). "Insulin clearance has been shown to be associated with impaired glucose tolerance and obesity." (PMID 40391305, 2025). "Indeed, hypothalamic iNOS overexpression triggers brain IR and obesity through mechanisms involving the S-nitrosylation of insulin signalling-associated molecules such as IRS-1 and AKT." (PMID 40243721, 2025). "Moreover, the authors demonstrated additional obesity‐associated factors, such as leptin and insulin, as possible drivers of DNA damage." (PMID 40523654, 2025). "This increased mortality risk may be driven by obesity‐related metabolic dysfunction, which exacerbates hepatic inflammation and fibrosis through mechanisms such as insulin resistance and adipokine dysregulation." (PMID 40236938, 2025). "The severity of hyperinsulinemia and IR sufficiently impacts the phenotype of PCOS and is considerably regulated by the interplay between genetic (such as polymorphism in the insulin gene regulatory region) and environmental factors, particularly diet-related obesity." (PMID 40486662, 2025). "The chronic increase in free fatty acids associated with obesity may increase insulin demand by pancreatic beta cells and induce intrinsic beta cell dysfunction through endoplasmic reticulum (ER) stress." (PMID 40561274, 2025). "High salt intake may be a contributor to obesity and diabetes, and dietary fat, especially trans fatty acids and saturated fats, is positively associated with T2D and obesity risks due to its effects on insulin sensitivity." (PMID 40630535, 2025). "Furthermore, obesity is associated with increased basal lipolysis and impaired insulin‐mediated FFA suppression, especially in upper body fat, contributing to systemic metabolic disturbances." (PMID 40968591, 2025). "This surgical approach offers more than just weight reduction; it substantially improves metabolic health by reducing lipotoxicity in the liver and skeletal muscles and attenuating the proinflammatory environment associated with obesity, an effect which is linked to decreased insulin resistance." (PMID 40707821, 2025). "Notably, Prevotella copri has been associated with obesity, increased fasting blood glucose, and elevated insulin levels." (PMID 40444006, 2025). "Improvements in blood pressure, insulin sensitivity, and obesity, which were pivotal thrombosis risk factors, may further mediate its protective effects." (PMID 40236289, 2025). "SNPs in the adiponectin, C1q, and collagen domain-containing (ADIPOQ) gene (rs2241766, rs1501299) are associated with reduced susceptibility to multiple obesity phenotypes, underscoring the importance of their encoded lipocalins in insulin sensitivity and inflammatory regulation." (PMID 41340654, 2025). "Moreover, the PPARG gene that influences energy balance is suggested as a risk locus for obesity and defective insulin signaling." (PMID 39859066, 2025). "BS may provide significant benefits in T1DM patients with obesity, including substantial weight loss, reduced insulin requirements, and metabolic improvements." (PMID 40707821, 2025).
Obesity (continued). "Furthermore, obesity is an independent risk factor for endocrine disruption: elevated blood serum total testosterone and insulin levels and reduced SHBG concentration levels." (PMID 40491594, 2025). "This reciprocal relationship may create a metabolic cycle that disrupts insulin signaling and impairs both innate and adaptive immune responses associated with obesity." (PMID 40806082, 2025). "Isopropyl-D-aposide, a glycoside compound, is hypothesized to potentially reduce the risk of obesity by alleviating oxidative stress and chronic inflammation, thereby improving insulin sensitivity and energy metabolism." (PMID 40893191, 2025). "Likewise, deactivation of MAPK10 in neurons induces weight gain and alters insulin and leptin signaling, characteristics associated with obesity." (PMID 40140215, 2025). "Consequently, AT macrophages secrete high levels of proinflammatory cytokines, resulting in obesity-associated chronic low-grade inflammation and impaired insulin signaling." (PMID 40308696, 2025). "We present a network constructed between obesity and different risk factors, based on the interactions of mitochondrial biogenesis, inflammatory pathways, insulin signaling and the expression of type 1 and 2 macrophages as well as different bioactive compounds." (PMID 40433407, 2025). "Glyoxalase 1 (Glo1) has been linked to obesity, glycemic control, insulin sensitivity, aortic endothelial cell dysfunction, non-alcoholic fatty liver disease (NAFLD), skeletal muscle dysfunction and CVD, suggesting its importance in regulating metabolic health." (PMID 39896461, 2025). "These food components may promote weight loss or maintenance, reduce adiposity and potentially lower the risk of obesity through various pathways, including satiety, insulin sensitivity, reduced inflammation and gut microbiome modification." (PMID 41374072, 2025). "Exposure to chronic hyperinsulinemia may disrupt insulin transduction and is associated with defective oxidative glucose disposal, endothelial dysfunction and obesity in type 1 diabetes." (PMID 41285865, 2025). "Both substances contribute not only in anti-inflammatory processes but also in enhancing lipid metabolism, improving insulin sensitivity, and reducing fat accumulation, thereby optimizing adipose tissue function and lowering the risk of obesity and related diseases." (PMID 41293158, 2025). "Genetic deletion of RFP, whether globally or specifically in adipocytes, significantly attenuated HFD-induced obesity and associated metabolic dysfunction, including reduced adiposity, improved glucose tolerance and enhanced insulin sensitivity." (PMID 40968148, 2025). "In a previous review on humans obesity, increases in these proteins were positively related to body mass index, adipose tissue volume, and chronic low-level inflammation, and negatively associated with insulin sensitivity." (PMID 39795034, 2025). "Chronic hyperinsulinemia, commonly observed in obesity, can lead to the persistent stimulation of hypothalamic insulin receptors and disrupt normal insulin signaling, causing metabolic dysregulation and appetite imbalances, contributing to overeating and sustaining BW gain." (PMID 40141063, 2025). "This metabolic disease involves defects in insulin secretion and action, and is closely linked to obesity, genetic factors, and metabolic inflammation, and its complex pathologic mechanisms are driving the deepening of cutting-edge research in endocrine medicine." (PMID 40520185, 2025). "Obesity is a heterogeneous clinical entity with distinct subtypes based on underlying genetic architecture and clinical phenotypic biomarkers that include measures of insulin sensitivity, glycaemia, physical fitness, body composition, and cardiovascular risk." (PMID 39997710, 2025). "However, in certain people with IR, T2DM can also develop inversely before obesity, leading to raised insulin levels and increased hepatic glucose production-the actual causes of obesity." (PMID 40278960, 2025).
Obesity (continued). "Because obesity per se is associated with hyperinsulinemia and insulin plays a pivotal role as a regulator of crucial transcription factors, we hypothesized that obesity-induced hyperinsulinemia can upregulate adipocyte TPH2 expression." (PMID 40455408, 2025). "Berberine exhibits a broad spectrum of pharmacological activities that collectively influence key metabolic disturbances associated with obesity, insulin resistance, glucose homeostasis, and lipid metabolism, underscoring its potential as a multifaceted therapeutic agent in metabolic disorders." (PMID 40710568, 2025). "It is unclear whether SG deficiencies influence adipocyte metabolism, insulin signaling, or inflammation, factors critically relevant to obesity and metabolic syndrome." (PMID 40723892, 2025). "Targeted lipidomics indicated that WMSZY’s anti-obesity effect may be linked to cholesterol metabolism, adipocyte lipolysis, lipid digestion, insulin resistance, and glycerolipid metabolism." (PMID 41194880, 2025). "While inflammation is typically associated with increased energy expenditure and weight loss in conditions like cachexia, obesity is characterized by chronic low-grade inflammation that contributes to insulin resistance and metabolic dysregulation, thereby hindering weight loss." (PMID 40573083, 2025). "Consumption of RS2 from high‐amylose maize improves insulin sensitivity in men with obesity at daily doses of 15–30 g, and promotes weight loss in overweight or obesity conditions and decreases liver triacylglycerols (TAGs) in people with NAFLD at a daily dose of 40 g." (PMID 40926357, 2025). "We assessed if fasting plasma insulin levels in pregnant women with obesity are associated with newborns’ abdominal fat deposition (dual-energy X-ray absorptiometry) and with cord blood DNA methylation (450k array) in 232 mother–child pairs from the Treatment of Obese Pregnant women (TOP) study." (PMID 40646607, 2025). "Significant reductions in weight and obesity were observed across the entire exercise group; Improvements were also noted in insulin sensitivity, lipid profiles, cardiorespiratory health, and levels of adipose factors associated with insulin sensitivity." (PMID 39931238, 2025). "Moreover, the positive energy balance associated with obesity induces a variety of metabolic factors such as insulin and insulin-like growth factor-1, which alter the nutritional milieu and create an environment conducive to tumor initiation and progression." (PMID 40904778, 2025). "Since skeletal muscle accounts for 80% of insulin-stimulated glucose disposal, and that obesity is associated with increasing insulin resistance in muscle tissue, maintaining muscle mass while reducing total fat and VAT should always be advised when loss of weight is recommended." (PMID 40260421, 2025). "Among these, key regulators of insulin signaling and metabolism may be particularly relevant in the context of the obesity risk." (PMID 40243885, 2025). "The underlying physiological mechanism may involve obesity, insulin resistance, and sarcopenia converging on a shared pro-inflammatory pathway, triggering an inflammatory cascade that impairs muscle metabolism and function." (PMID 40055243, 2025). "Obesity is often associated with abnormal insulin levels and disrupted glucose metabolism." (PMID 40239869, 2025). "Deficiency reduces obesity-associated inflammation and improves insulin sensitivity." (PMID 41488667, 2025). "Some cross-sectional studies have shown that AT oxygenation was positively associated with insulin sensitivity in individuals with obesity, whereas others found an inverse association between AT oxygenation and insulin sensitivity in men and women, independent of adiposity." (PMID 39298040, 2025).
Obesity (continued). "BZA/CE reduced adiposity, enriched small (insulin-sensitive) mammary adipocytes, increased the abundance of beneficial metabolic gut microbes (Faecalbaculum rodentium and Odoribacter laneus), and reversed obesity-associated changes in lipids and adipokines." (PMID 40048260, 2025). "The functional significance of the increased insulin‐stimulated BGU associated with obesity/IR is currently unknown." (PMID 40926735, 2025). "Similarly, MSNA burst frequency was significantly associated with markers of obesity, plasma insulin, and the HOMA index." (PMID 41017376, 2025). "The underlying mechanism may be that early-stage obesity induces a series of metabolic abnormalities, including reduced peripheral glucose uptake, insulin resistance, and glucotoxicity, ultimately leading to elevated blood glucose levels." (PMID 40599621, 2025). "It was found that as BMI increased, pancreatic islet volume, insulin secretion, and C-peptide content also increased, suggesting that obesity might be associated with better outcomes of β-cell function." (PMID 40426908, 2025). "Higher circulating adiponectin levels are associated with increased insulin sensitivity and reduced hepatic fat accumulation in individuals with obesity and type 2 diabetes, whereas low adiponectin levels are indicative of metabolic dysfunction across diverse populations." (PMID 41156477, 2025). "Furthermore, in T1D, the intra-islet regulation of glucagon secretion by insulin is lost, and the prevalence of obesity, dyslipidemia, depression, and other risk factors for CVD is increased." (PMID 39998445, 2025). "Also, low physical activity can cut energy expenditure, raising the risk of weight gain and obesity, which in turn affects glycemic control and insulin sensitivity." (PMID 40655203, 2025). "Obesity is, also, associated with increased serum insulin levels." (PMID 40523654, 2025). "Altered asprosin signaling, previously linked to DM, obesity, and other metabolic disorders, may exacerbate COVID-19 severity through effects on systemic inflammation, insulin sensitivity, and hepatic glucose production." (PMID 41286678, 2025). "Decreased ghrelin levels in obesity have been associated with increased insulin levels." (PMID 39813443, 2025). "Our results suggest a complex interplay between diet, obesity, and the risk of EC, in which insulin-related pathways may play an etiological role." (PMID 40431387, 2025). "vWAT tends to cause low-grade inflammation that promotes insulin resistance and is responsible for the morbidity associated with obesity, whereas sWAT is metabolically active with less inflammatory activity, and could favor metabolic insulin action." (PMID 41011119, 2025). "Insulin/IGF-1 signaling contributes to obesity-associated cancer risk." (PMID 41296433, 2025). "As we also found higher IGF-1 concentrations in fatter compared to leaner cats, we speculate that this could be related to systemic alterations associated with overweight/obesity, for example alterations of the insulin-IGF axis." (PMID 40001060, 2025). "These mice exhibited typical metabolic characteristics associated with obesity, including significant increases in body weight, adipose tissue mass, blood glucose levels, fasting serum leptin level, and fasting serum insulin level." (PMID 40160428, 2025). "Thus, the tendency toward higher insulin levels in subjects with obesity carrying the A allele of the TNF-α gene, compared to those with the GG genotype, has not been universally observed." (PMID 40732969, 2025). "The findings suggest that genistein supplementation may offer a novel therapeutic strategy for improving insulin sensitivity in individuals with obesity, a key risk factor for T2DM." (PMID 40076293, 2025). "On the other hand, mutations that reduce PTEN activity may increase insulin sensitivity, but they also raise the risk of obesity and cancer." (PMID 41296433, 2025).
Obesity (continued). "More complex lipids were associated with insulin sensitivity (n = 124) than obesity per se (n = 7)." (PMID 41456639, 2025). "The ECSCR gene plays a role in the regulation of insulin sensitivity and susceptibility to obesity." (PMID 40362161, 2025). "Indeed, obesity is associated with increased adipose tissue, metabolic disturbances (hyperglycemia), higher levels of insulin, and insulin-like growth factors (IGFs), with potent mitogenic activity." (PMID 41278286, 2025). "Furthermore, prenatal exposure to androgens has been linked to impaired insulin sensitivity, an increased risk of obesity, and metabolic dysfunction in offspring, particularly in female children." (PMID 40076815, 2025). "Early studies have reported an increased proportion of CD56brightCD16− NK cells in VAT in the context of obesity, yet the precise contributions of obesity-associated CD56dim and CD56bright NK cell subsets to the initiation of inflammation and insulin resistance remain an open question." (PMID 41425544, 2025). "We postulate that the brain response to insulin adapts to short-term changes in diet before weight gain and may facilitate the development of obesity and associated diseases." (PMID 39984682, 2025). "Moreover, MCHC has been linked to metabolic disorders, with levels increased in obesity and decreased by medications improving cellular insulin sensitivity." (PMID 39940380, 2025). "Furthermore, obesity-caused adipocyte hypertrophy is additionally associated with reduced insulin sensitivity and a variation in the expression and secretion of adipokines and cytokines." (PMID 40498013, 2025). "Numerous studies confirm that obesity is associated with systemic inflammation: interferon-stimulated genes are upregulated in the blood of insulin-resistant subjects, and extracellular matrix and proinflammatory genes are increased in adipose tissue in the setting of visceral adiposity." (PMID 41303351, 2025). "Beyond LEP and insulin, a broader spectrum of hormonal imbalances, including changes in adipokines, gut hormones, and neuroendocrine regulators, has been implicated in the systemic dysfunction characteristic of obesity." (PMID 41226484, 2025). "In humans, D-lactate is more closely associated with obesity than with insulin resistance, which may explain its rise during CAF feeding." (PMID 41305664, 2025). "Although speculative, INSR plays a role in insulin signalling, and its linkage to ccRCC raises the possibility that it may in part mediate the obesity associated risk of RCC." (PMID 41326661, 2025). "The statement highlights that skipping breakfast and irregular eating patterns are associated with adverse outcomes, including higher obesity rates, impaired insulin sensitivity, and increased blood pressure, with some evidence suggesting potential negative effects on lipid profiles." (PMID 40869791, 2025). "Regarding an emerging area of concern, youth with both obesity and with T1D may be at risk of developing insulin resistance to their exogenous insulin, increasing their risk for macro- and micro-vascular complications and additional weight gain." (PMID 40688480, 2025). "Obesity-associated hyperactivation of the insulin/Insulin-like Growth Factor 1 (IGF-1) signaling pathway further facilitates tumor cell energy metabolic reprogramming and protein synthesis through the mTORC1 pathway, thereby providing the bioenergetic foundation for liver metastasis." (PMID 41164182, 2025). "This shows that increasing insulin signaling in the adipose tissue may be a viable therapeutic strategy for metabolic diseases associated with obesity." (PMID 40141412, 2025). "In addition to its role in insulin sensitivity, magnesium deficiency was also significantly associated with obesity, suggesting a broader contribution to metabolic dysregulation." (PMID 40895688, 2025).